SPIDR (scaffold protein involved in DNA repair)
Description:
Involved in early stages DNA double-strand break (DSB) repair via homologous recombination (HR). As part of the Shu complex, promotes HR by regulating replication protein-A (RPA) dynamics on single-stranded DNA, thereby stabilizing RAD51 and DMC1 filaments on DNA. The Shu complex is essential during meiosis by stabilizing DMC1 filaments. In contrast, it is critical for only certain types of homologous-directed DNA repair, such as inter-homolog homologous recombination (IR-HR). IR-HR is a DNA repair mechanism where a cell repairs a DSB on one chromosome using the matching homologous chromosome as a template, rather than the sister chromatid.
Synonyms: KIAA0146; ODG9
Tractability: PROTAC: ubiquitination databases record sites on it.
Gene: Protein-coding gene on chromosome 8 (47,260,878 to 47,736,306, forward strand). Ensembl gene ENSG00000164808.
Subcellular location: Chromosome; Nucleus
Subcellular location (Human Protein Atlas): Nucleoplasm
Pathways (Reactome):
DNA Repair: Resolution of D-loop Structures through Holliday Junction Intermediates
Gene Ontology:
Molecular function: protein binding
Biological process: cellular response to camptothecin; cellular response to hydroxyurea; cellular response to ionizing radiation; DNA damage response; DNA recombinase assembly; double-strand break repair via homologous recombination; positive regulation of double-strand break repair; positive regulation of protein-containing complex assembly; regulation of double-strand break repair via homologous recombination; regulation of establishment of protein localization to chromosome; double-strand break repair involved in meiotic recombination; homologous chromosome pairing at meiosis
Cellular component: nuclear chromosome; nucleoplasm; Shu complex; chromosome; nucleus
Genetic constraint (gnomAD): Loss-of-function variants: 71 observed, 88.44 expected, observed/expected ratio (o/e) 0.8, 90% interval 0.66 to 0.98. The upper end of that interval is the gene's LOEUF score, 0.98, which puts it in group 4 of 6, group 1 being the genes least tolerant of losing a copy. Missense variants: 1,038 observed, 1,065.4 expected, observed/expected ratio (o/e) 0.97, 90% interval 0.93 to 1.03. Synonymous variants: 387 observed, 404.33 expected, observed/expected ratio (o/e) 0.96, 90% interval 0.88 to 1.04.
Homologues: Orthologues: chimpanzee SPIDR (99% identical), macaque SPIDR (83% identical), rabbit SPIDR (72% identical), pig SPIDR (67% identical), mouse Spidr (65% identical), rat Spidr (63% identical), tropical clawed frog spidr (39% identical), dog SPIDR (31% identical).
Diseases named in the same sentence as SPIDR in open-access papers:
SPIDR is named in the same sentence as 15 diseases in open-access papers, as found by Europe PMC text mining. Sharing a sentence is not in itself a finding about the gene and the disease. The quoted sentences say what the papers report.
breast carcinoma (1 paper, 2022). "SPIDR was significantly increased in breast cancer tissues compared to their normal counterparts, which was not responsible for the downregulation of circRNA-CREIT." (PMID 36038948, 2022).
cervical adenocarcinoma (1 paper, 2022). An adenocarcinoma arising from the cervical epithelium. "CircRNA-CREIT is derived from exons 6 and 7 of the SPIDR gene, which was recently reported to act as a tumor suppressor in cervical adenocarcinoma." (PMID 36038948, 2022).
infertile (1 paper, 2025). "This case is of particular interest due to the rarity of SPIDR-associated POI: only three infertile females with biallelic SPIDR variants have been described up to date." (PMID 41393291, 2025).
male infertility (1 paper, 2025). The inability of the male to effect fertilization of an ovum after a specified period of unprotected intercourse. "Similar to the variants in the STAG3 gene, biallelic variants in the SPIDR gene cause both female and male infertility." (PMID 41393291, 2025).
ovarian carcinoma (1 paper, 2016). A malignant neoplasm originating from the surface ovarian epithelium. "SPIDR is a scaffolding protein that is involved in homologous recombination repair mechanism and is shown to have breast and ovarian cancer susceptibility." (PMID 28117658, 2016).
ovarian failure (1 paper, 2025). "A causal role may also be attributed to mutations in the homologous recombination repair gene SPIDR gene, whose alteration has been associated with gonadal disgenesia and ovarian failure." (PMID 41458559, 2025).
tumor (4 papers, 2015 to 2024). "To explore the mechanisms underlying circRNA-CREIT downregulation, we detected the SPIDR levels in tumor tissues." (PMID 36038948, 2022). "Then, we analyzed the expression of NRF1 and SPIDR in different tumor grades based on the TCGA-LIHC dataset." (PMID 38438958, 2024).
SPIDR also shares sentences with these, for which no sentence is quoted: cancer (2 papers); Alzheimer disease (1); amyotrophic lateral sclerosis (1); Bloom syndrome (1); Fanconi anemia (1); hepatocellular carcinoma (1); neurodegenerative disease (1); Parkinson disease (1).